CCL2 (C-C motif chemokine ligand 2)
Diseases named in the same sentence as CCL2 in open-access papers (continued):
Sharing a sentence is not in itself a finding about the gene and the disease.
trachoma (3 papers, 2008 to 2024). "The chemokine monocyte chemoattractant protein-1 (CCL2) has also been identified in chronic chlamydial infections demonstrating elevated levels in post-scarring trachoma populations." (PMID 22894815, 2012). "Chemokine protein levels for CCL11 (Eotaxin), CXCL8 (IL-8), CXCL9 (MIG), and CCL2 (MCP-1) were elevated in chronic scarring trachoma compared with age and sex matched controls (P<0.05, for all)." (PMID 18628987, 2008).
urolithiasis (3 papers, 2018 to 2021). Stone(s) within the urinary tract. "C-C motif chemokine ligand 2 (CCL-2) is a chemokine and osteopontin (OPN) are also beneficial to urolithiasis." (PMID 29236151, 2018).
Acidosis (2 papers, 2020 to 2025). Abnormal acid accumulation or depletion of base. "Acidosis decreased the gene expression of the pro-inflammatory markers Nos2, Ccl2, and IL-6 in IFN-γ/lipopolysaccharide-polarized macrophages, and it increased the expression of anti-inflammatory markers CD206 and Arg1 in IL-4-polarized macrophages." (PMID 32823915, 2020). "Acidosis-induced RASF elevates the transcription levels of numerous cytokines, encompassing classical innate immune cell chemotactic combinations such as CCL2, IL8, and CCL5, along with inflammatory cytokine combinations like IL6 and IL12, which are contingent upon adaptive immune responses." (PMID 40234753, 2025).
acute GVHD (2 papers, 2013 to 2024). "In a recent study, we investigated whether the pretransplant serum cytokine profile (including the chemokines CCL2/3/4/5/11 and CXCL5/8/10/11) was associated with the development of serious posttransplant complications, i.e., early multiorgan failure or severe acute GVHD." (PMID 23430540, 2013). "Additionally, CCL2/CCR2 also mediates the migration of activated macrophages to the mucosal surface, closely related to the tissue destruction observed in oral acute GVHD." (PMID 39840040, 2024). "Similarly, elevated levels of CCL2, CCL3, and CCL5 in the liver and intestines of acute GVHD mice mediate the infiltration of neutrophils and activated T cells." (PMID 39840040, 2024).
acute tubular necrosis (2 papers, 2018 to 2024). "Co-localization studies showed that areas with nitrotyrosine and CCL2 immunoreactivity coincided in kidney tissue sections of ischemia and reperfusion-induced acute tubular necrosis patients." (PMID 30233568, 2018).
Airway obstruction (2 papers, 2010 to 2018). Obstruction of conducting airways of the lung. "RSV RNA loads were detected in peripheral blood from day 1 to 14 post-inoculation, peaked on day 5 and significantly correlated with nasal and lung RSV loads, airway obstruction, and blood CCL2 and CXCL1 expression." (PMID 20843364, 2010).
aspergillosis (2 papers, 2020 to 2023). Aspergillosis is an infection, growth, or allergic response caused by the Aspergillus fungus. "Morrison and coworkers observed that CCL2 was involved in NK-cell recruitment into the lungs during aspergillosis, and Hokerness and coworkers showed that this NK-cell recruitment required CCL2 plus its receptor, CCR2." (PMID 36902456, 2023). "The chemokines (CCL3, CCL2, and CCL5) followed in this study have been previously shown to be associated with aspergillosis since they are involved in the recruitment of neutrophils, platelets, and monocytes, but the molecules responsible for the chemokine production have not been identified." (PMID 31915215, 2020).
atopic asthma (2 papers, 2018 to 2021). An asthma that is characterized by symptoms that are triggered by an allergic reaction caused by inhaled allergens such as dust mite allergen, pet dander, pollen and mold. "We speculate that IL2RG and CCL4 might be important genes related to childhood atopic asthma, and together with CCL2 participate in the cytokine receptor interaction signaling pathway that plays a role in childhood atopic asthma." (PMID 34525985, 2021). "Both CCL2 and CCL20 have been proposed as pivotal in the increased steady-state numbers of DCs in the bronchial mucosa of patients with asthma, with a notable increase in Der p 1–dependent CCL20 release in airway samples in atopic asthma." (PMID 29976563, 2018).
Behçet's syndrome (2 papers, 2017 to 2022). "Our study confirms earlier data presenting the absence of an association between the chemokine genes rs1024610/CCL2 and rs2280788/rs2107538/CCL5 with Behcet's disease or retinal vasculitis in patients from UK." (PMID 28589131, 2017).
benign breast diseases (2 papers, 2018 to 2023). "We are able to establish CCL2 as differentiation maker between malignant and benign breast diseases." (PMID 30151375, 2018).
Blindness (2 papers, 2011 to 2015). Blindness is the condition of lacking visual perception defined as a profound reduction in visual perception. "Ocular localization of the proteins that showed significantly higher expression in the vitreous than in blood (CCL2, IGFBP2, MMP10, HGF, TNFRSF11B) was investigated in histological specimens of eyes from patients with painful blindness due to secondary glaucoma after CRVO." (PMID 25978399, 2015).
bone marrow fibrosis (2 papers, 2021 to 2023). "Higher levels of IL-1α and β, IL-6, IL-8, IL-13, MCP-1/CCL2, and TGF-β correlate with a higher degree of bone marrow fibrosis." (PMID 37760903, 2023).
bronchiolitis obliterans syndrome (2 papers, 2016 to 2018). A lung disorder that is mainly associated with chronic allograft dysfunction after lung transplantation and that is characterized by inflammation and fibrosis of bronchiolar walls that reduce the diameter of the bronchioles and result in progressive and irreversible airflow obstruction. "We previously generated a mouse model overexpressing CCL2, which generates organizing pneumonia-like changes, morphologically comparable to human patients." (PMID 27282780, 2016). "We analyzed the similarities and differences of fibrosis-associated gene expression in individual compartments from patients with organizing pneumonia and transgenic (CCL2) mice using laser-assisted microdissection, real-time PCR and immunohistochemistry." (PMID 27282780, 2016). "We suggest that the CCL2-overexpressing transgenic mouse model (CCL2 Tg mice) is suitable for further investigation of fibrotic pulmonary remodeling, particularly of organizing pneumonia pathogenesis and for the search for novel therapeutic strategies." (PMID 27282780, 2016). "Hence, the transgenic CCL2 mouse model shows not only pathogenomic and morphological features of human organizing pneumonia but also a similar inflammatory profile." (PMID 27282780, 2016).
CADASIL (2 papers, 2023 to 2025). "Previous studies have detected systemic inflammatory cytokines, including IL-1β, IL-6, TNF-α, CCL2, and CXCL16, and found that their expression levels were significantly elevated in CADASIL patients, which is consistent with our results." (PMID 41000387, 2025). "The serum inflammatory cytokines were analyzed by ELISAs and revealed that the levels of serum IL-1β, IL-6, TNF-α, CCL2, and CXCL16 were significantly elevated in the patient group compared with their family members, suggesting a systemic inflammation in CADASIL patients." (PMID 37684694, 2023).
cartilage disorders (2 papers, 2017 to 2024). "Regarding the similar role of CCL2 in the pathogenesis of RA and OA, CCN1 inhibition could serve as a potential strategy via reducing the CCL2/CCR2 axis-mediated inflammation in these bone and cartilage disorders." (PMID 39076996, 2024).
Chlamydia infection (2 papers, 2021 to 2023). "Following Chlamydia infection, mast cell-deficient mice displayed attenuated CXCL2 production, with the levels of other proinflammatory mediators including CCL2, CCL5, CXCL13, and effector mediators assessed as not being significantly altered." (PMID 37138882, 2023).
chlamydial infection (2 papers, 2012 to 2014). "Due to the involvement of CCL2 with acute and chronic grades of chlamydial infections and its association with a Th2-mediated response, we evaluated the effect of 405 nm photo treatment on its production." (PMID 22894815, 2012).
Chronic cholecystitis (2 papers, 2016 to 2022). "Chronic cholecystitis led to an adapted microenvironment characterized by MDSC-like macrophages, CD8+ TRM cells, and CCL2+ immunity-regulating fibroblasts." (PMID 36198671, 2022).
chronic hepatitis B (2 papers, 2013 to 2020). "Serum CCL2 was significantly higher in HCC patients in a study that measured CCL2 levels from serum samples from 98 resectable HCCs, 101 patients with chronic hepatitis B, and 100 asymptomatic hepatitis B and C virus carriers." (PMID 33297571, 2020).
chronic myeloproliferative disorders (2 papers, 2018 to 2024). "Within the context of myeloproliferative disorders, CCL2 and its associated signaling pathways may play a critical role." (PMID 39850880, 2024).
chronic viral hepatitis (2 papers, 2013 to 2024). "Moreover, during the development of chronic viral hepatitis and MASH, CCL2 and CCL5 played an important role." (PMID 39605886, 2024).
cocaine addiction (2 papers, 2015 to 2025). "CALM3 and JUN were downregulated in the cocaine addiction group compared to controls (p < 0.05), whereas CCL2, CD44, CLIC1, and VCAM1 were upregulated (p < 0.05)." (PMID 41465087, 2025). "However, the plasma concentrations of CCL2 were significantly affected by history of cocaine addiction (F1,122 = 42.03, p < 0.001)." (PMID 25762940, 2015). "The results showed that the concentrations of chemokine (C-C motif) ligand 2/monocyte chemotactic protein-1 (CCL2/MCP-1) and chemokine (C-X-C motif) ligand 12/stromal cell-derived factor-1 (CXCL12/SDF-1) were only affected by history of cocaine addiction." (PMID 25762940, 2015). "The strong positive correlations observed between genes like CCL2, CD44, and CXCL8 further suggest coordinated regulation of immune processes in cocaine addiction, which may be modulated by exercise." (PMID 41465087, 2025).
colon adenoma (2 papers, 2021 to 2025). An adenoma that arises from the colon. "Intratumoral CCL2 expression levels have been reported in CRC patients and accumulation of MDSC induced by CCL2 correlated with the development and growth of colon adenoma." (PMID 34381456, 2021).
colorectal polyps (2 papers, 2021 to 2022). "Colorectal polyps are characterized by a significantly higher content of MCP-1, MCP-2, and MCP-3 proteins but a lower number of the respective CCL2, CCL7, and CCL8 transcripts, the downregulation of which is more pronounced in polyps with greater potential for malignancy." (PMID 34884259, 2021).
colorectal tumors (2 papers, 2011 to 2021). "Therefore, the overexpression of JAK/STAT in colorectal tumors, reported elsewhere and positively associated with cancer advancement and poor prognosis, may explain the lower CCL2 expression in tumors compared to tumor-adjacent tissue observed in the present study." (PMID 34885960, 2021). "Tumour conditioned media obtained from cultured colorectal tumour explant tissue contained high levels of the chemokines CCL2, CXCL1, CXCL5 in addition to VEGF." (PMID 22125641, 2011).
cystic kidney disease (2 papers, 2023). A congenital or acquired kidney disorder characterized by the presence of renal cysts. "Cytokines including CCL2, CSF1 and CX3CL1 are associated with inflammation in cystic kidney diseases." (PMID 36457161, 2023).
deafness (2 papers, 2014 to 2020). An inherited or acquired condition characterized by the complete loss of the ability to hear from one or both ears. "The expression of IL-6 and CCL-2 was higher in the permanent hearing damage model than in the temporary hearing damage model, suggesting that the inflammatory response is a potential therapeutic target for the treatment of deafness resulting from energy failure in the lateral cochlear wall." (PMID 24614528, 2014). "In noise-induced deafness, proinflammatory cytokines or chemokines, including TNF-α, IL-1β, IL-6, Icam-1, and Ccl2, were increased in cells of the stria vascularis or lateral wall." (PMID 33505961, 2020).
degenerative disc disease (2 papers, 2020 to 2025). "Our study has several major strengths that enhance the understanding of intervertebral disc degeneration and its associated pain mechanisms, particularly the β‐catenin and CCL2 pathways, by utilizing the Agc1‐CreERT2/Sox9flox/flox mouse model." (PMID 40012719, 2025). "This study investigates the mechanism of intervertebral disc degeneration via the β‐catenin/CCL2 pathway in Sox9 conditional knockout mice." (PMID 40012719, 2025). "We demonstrate that the Sox9 regulation of β‐catenin, CCL2, and GDNF constitutes a pivotal mechanism in pain signaling, suggesting that modulation of this pathway may represent a promising therapeutic strategy for intervertebral disc degeneration and its concomitant pain." (PMID 40012719, 2025).
dystrophin deficiency (2 papers, 2021 to 2022). "Elevated serum CCL2 not only provides us with a non-invasive serum biomarker of dystrophin deficiency in the DE50-MD model, but also a potential therapeutic target." (PMID 36444978, 2022). "To verify if the increased levels of these three chemokines are effectively associated with dystrophin deficiency, we conducted ELISA assays to measure CCL2 and CXCL10 on serum samples collected from mdx-23 mice (n = 10) and wild-type mice (n = 14)." (PMID 34440571, 2021). "Interestingly, CCL2, but not CXCL10, was significantly elevated in serum samples of the mdx mouse model for DMD relative to wild-type mice, further suggesting that increased levels of this circulating CCL2 may be associated with muscle pathogenesis due to dystrophin deficiency." (PMID 34440571, 2021).
eosinophilic leukemia (2 papers, 2011 to 2012). "Recent studies have described the tumor-promoting roles of CCL2/MCP-1 in eosinophilic leukemia EoL-1 cells and breast cancel cells." (PMID 22248096, 2012).
ependymoma (2 papers, 2021 to 2025). A WHO grade II, slow growing tumor of children and young adults, usually located intraventricularly. "We noticed that microglia from the normal brain showed high expression of CCL2 and CCL3, resembling tissue-resident CCL2+ TAMs in ependymoma." (PMID 34824203, 2021). "CCL2+ TAMs, representing the activated TAMs in the TME, were more likely to interact with immune cells and showed a high immune-response capacity, implying their antitumor roles in ependymomas." (PMID 34824203, 2021).
epididymitis (2 papers, 2022 to 2023). Inflammation of the epididymis. "Interestingly, some DEGs in murine model such as IL-1, CCL2 was not identified in our study, suggesting the species variation or different epididymitis models and emphasizing the importance of collecting clinic samples." (PMID 35634321, 2022).
Ewing sarcoma (2 papers, 2016 to 2024). A small round cell tumor that lacks morphologic, immunohistochemical, and electron microscopic evidence of neuroectodermal differentiation. "Moreover, many pediatric neuroblastoma, Ewing sarcoma (ES), osteosarcoma, and ALL, show altered expression of circulating cytokines/chemokines such as CCL2, CXCL4, CXCL6, CXCL10, and CXCL12." (PMID 38927907, 2024).
follicular lymphoma (2 papers, 2018 to 2023). Follicular lymphoma is a form of non-Hodgkin lymphoma characterized by a proliferation of B cells whose nodular structure of follicular architecture is preserved. "Investigators have demonstrated that marrow MSCs from patients with follicular lymphoma, which has a relatively high rate of marrow involvement, overexpress chemokine (C-C motif) ligand 2 (CCL2) and aid in sustaining the growth of malignant B cells." (PMID 30101129, 2018).
fracture (2 papers, 2017). "A PPI network was constructed with 167 nodes and 233 edges, and module analysis demonstrated that CCL2, CSF2, NOS2, and DLC1 may stimulate bone overgrowth after femoral fracture via anti-apoptosis-related functions." (PMID 28095896, 2017).
fragile X syndrome (2 papers, 2017 to 2023). A genetic syndrome caused by mutations in the FMR1 gene which is responsible for the expression of the fragile X mental retardation 1 protein. "The higher levels of CCL2 and CCL5 were detected in ASD patients while lower plasma levels of these genes were detected in ASDs with fragile X syndrome." (PMID 36691005, 2023).
granulomatosis with polyangiitis (2 papers, 2016 to 2021). A small-vessel necrotizing vasculitis characterized by the association of inflammation of the vessel wall and peri- and extravascular granulomatosis. "Proteinase 3 (PR3), which is mainly produced by neutrophils and is the main autoantigen in granulomatosis with polyangiitis, binds also to endothelium and induces CXCL8 (IL-8) and CCL2 (MCP-1) that provide chemotactic signals for neutrophils and monocytes." (PMID 28018358, 2016).
hemolytic-uremic syndrome (2 papers, 2022). Acute kidney injury associated with microangiopathic hemolytic anemia and thrombocytopenia. "Upregulation of CCL2 and CCL5, and to a lesser extent CCL3, was also shown to mediate the accumulation of macrophages in kidney in a mouse model of the hemolytic-uremic syndrome." (PMID 35203629, 2022).
hemorrhagic stroke (2 papers, 2021 to 2025). A stroke caused by a bleed on the brain. "Induced expression of both CXCL10 and CCL2 has also been observed in human cases of ischemic and hemorrhagic stroke." (PMID 40867143, 2025).
histiocytic sarcoma (2 papers, 2016 to 2022). An aggressive malignant neoplasm with a poor response to therapy, usually presenting as stage III/IV disease. "While we focused on IL-6 and CCL2, many of the other genes identified are also highly interesting and should provide significant insight related to histiocytic sarcoma pathogenesis." (PMID 27105514, 2016). "Significant increases in serum CCL2 levels have been found in canine cases of disseminated histiocytic sarcoma." (PMID 27105514, 2016). "In this prior study, serum levels of CCL2 were significantly increased in dogs diagnosed with disseminated histiocytic sarcoma compared to healthy control animals." (PMID 27105514, 2016). "Increased CCL2 has been previously reported in veterinary patients with histiocytic sarcoma." (PMID 27105514, 2016). "Likewise, Ccl2 appears to be up-regulated in macrophages from Nlrx1−/− mice and was identified as being one of the genes with the greatest level of up-regulation in the spleen during histiocytic sarcoma." (PMID 27105514, 2016).
Hodgkin’s disease (2 papers, 2022 to 2023). "As classical Hodgkin lymphoma shares many characteristics with acute inflammatory processes, NF-kB signaling plays a major role by mediating the immediate-early expression of various cytokines including the chemokine CCL2." (PMID 36831273, 2023).
Hydrocephalus (2 papers, 2019 to 2021). Hydrocephalus is an active distension of the ventricular system of the brain resulting from inadequate passage of CSF from its point of production within the cerebral ventricles to its point of absorption into the systemic circulation. "In patients with possible normal pressure hydrocephalus, median ventricular CSF concentrations were reported for IL-8 (19.1 [11.0] pg/mL), TNF-alpha, and CCL2 (758 [264.0] pg/mL)." (PMID 34439789, 2021).
hyperparathyroidism (2 papers, 2017 to 2023). Hyperfunction of the parathyroid glands resulting in the overproduction of parathyroid hormone. "In hyperparathyroidism, monocyte chemoattractant protein 1 (MCP‐1, CCL2) levels are increased, as are those of RANKL." (PMID 36751417, 2023).
insulinoma (2 papers, 2012 to 2017). "In 832/13 rat insulinoma cells, we observed that 1 ng/mL IL-1β is sufficient to drive maximal expression of the CCL2 gene, as increasing the amount 10-fold to 10 ng/mL does not promote additional mRNA accumulation." (PMID 23056550, 2012).
Kaposi's sarcoma (2 papers, 2017 to 2020). A malignant neoplasm characterized by a vascular proliferation which usually contains blunt endothelial cells. "In addition, in Kaposi sarcomas D6/ACKR2 delays tumor progression through inhibition of inflammatory chemokines CCL-2, CCL-5 and CCL-3 and reduces macrophage infiltration and angiogenesis." (PMID 28740576, 2017).